SAMTOR (S-adenosylmethionine sensor upstream of mTORC1)
Description:
S-adenosyl-L-methionine-binding protein that acts as an inhibitor of mTORC1 signaling via interaction with the GATOR1 and KICSTOR complexes. Acts as a sensor of S-adenosyl-L-methionine to signal methionine sufficiency to mTORC1: in presence of methionine, binds S-adenosyl-L-methionine, leading to disrupt interaction with the GATOR1 and KICSTOR complexes and promote mTORC1 signaling. Upon methionine starvation, S-adenosyl-L-methionine levels are reduced, thereby promoting the association with GATOR1 and KICSTOR, leading to inhibit mTORC1 signaling. Probably also acts as a S-adenosyl-L-methionine-dependent methyltransferase (Potential).
Synonyms: BMT2; C7orf60; DKFZp762M126; FLJ31818
Tractability: PROTAC: ubiquitination databases record sites on it.
Gene: Protein-coding gene on chromosome 7 (112,819,147 to 112,939,875, reverse strand). Ensembl gene ENSG00000164603.
Subcellular location (Human Protein Atlas): Cytosol
Pathways (Reactome):
Cellular responses to stimuli: Amino acids regulate mTORC1
Gene Ontology:
Molecular function: protein-containing complex binding; S-adenosyl-L-methionine binding; methyltransferase activity
Biological process: cellular response to amino acid starvation; cellular response to methionine; positive regulation of TORC1 signaling; regulation of TORC1 signaling
Cellular component: cytosol
Genetic constraint (gnomAD): Loss-of-function variants: 10 observed, 33.46 expected, observed/expected ratio (o/e) 0.3, 90% interval 0.18 to 0.51. The upper end of that interval is the gene's LOEUF score, 0.51, which puts it in group 2 of 6, group 1 being the genes least tolerant of losing a copy. Missense variants: 348 observed, 447.69 expected, observed/expected ratio (o/e) 0.78, 90% interval 0.71 to 0.85. Synonymous variants: 173 observed, 159.84 expected, observed/expected ratio (o/e) 1.08, 90% interval 0.95 to 1.23.
Homologues: Orthologues: chimpanzee BMT2 (99% identical), macaque BMT2 (99% identical), dog SAMTOR (97% identical), pig SAMTOR (97% identical), rabbit SAMTOR (97% identical), mouse Samtor (94% identical), guinea pig SAMTOR (90% identical), rat Bmt2 (78% identical), tropical clawed frog samtor (70% identical), zebrafish samtor (68% identical), Drosophila melanogaster Samtor (24% identical).
Diseases named in the same sentence as SAMTOR in open-access papers:
SAMTOR is named in the same sentence as 2 diseases in open-access papers, as found by Europe PMC text mining. Sharing a sentence is not in itself a finding about the gene and the disease. The quoted sentences say what the papers report.
cancer (3 papers, 2018 to 2025). A tumor composed of atypical neoplastic, often pleomorphic cells that invade other tissues. "The differential regulation of mTORC1 by amino acid sensors such as Sestrin2 (leucine), CASTOR1 (arginine), and SAMTOR (methionine) underscores the complexity of nutrient sensing in cancer." (PMID 40427696, 2025). "Given mTORC1’s established role in cellular aging and metabolism, SAMTOR emerges as a key regulator linking methionine availability to mTOR signaling and cancer progression." (PMID 40427696, 2025).
SAMTOR also shares sentences with these, for which no sentence is quoted: prostate carcinoma (1 paper).